HDAC9 (histone deacetylase 9)
Diseases named in the same sentence as HDAC9 in open-access papers (continued):
Sharing a sentence is not in itself a finding about the gene and the disease.
multiple myeloma (167 papers, 2008 to 2025). "HDAC IIa composes of HDAC4, HDAC5, HDAC7, and HDAC9, numbers of studies demonstrated HDAC IIa inhibition as an alternative approach to avoid the progression of various diseases, examples like breast tumors, pancreatic cancer, multiple myeloma, and type 2 diabetes." (PMID 35492337, 2022).
leukemia (159 papers, 2006 to 2026). A malignant (clonal) hematologic disorder, involving hematopoietic stem cells and characterized by the presence of primitive or atypical myeloid or lymphoid cells in the bone marrow and the blood. "An additional 20% of Eμ-HDAC9 mice either developed splenic B-cell lymphoma/leukemia (SBCL/L) or another hematological malignancy, such as histiocytic sarcoma." (PMID 27799148, 2016). "In contrast, deregulated MEF2D activity, with activation of HDAC9 and resulting inhibition of MEF2C were characteristic of this form of leukaemia." (PMID 27824051, 2016).
cutaneous T-cell lymphoma (150 papers, 2008 to 2026). "The HDAC9 protein is a member of the histone deacetylase family that can repress transcriptional regulation by catalyzing acetyl group removal from lysine residues and is associated with cutaneous T cell lymphoma and maxillary cancer." (PMID 35654793, 2022).
lung carcinoma (150 papers, 2007 to 2026). "Similar to our findings in other BRM-deficient cancer cells lines and primary lung cancers, we found that HDAC9 mRNA was overexpressed ~47±13-fold in Rhabdoid cell lines as measured by qPCR." (PMID 24913006, 2014). "HDAC9 is considered an oncogene in many kinds of cancer including oral squamous cell carcinoma, gastric cancer, lung cancer, and pancreatic ductal adenocarcinoma." (PMID 38093179, 2023). "HDAC9 expression was significantly positively correlated with CD8+ cell counts in human lung cancer stroma samples." (PMID 35359455, 2022). "The number of CD8+ cells in human lung cancer stroma samples positively correlates with the expression of HDAC9." (PMID 34318404, 2021). "We also observed that HDAC9 was overexpressed in Rhabdoid cancer cells as well as in lung cancer cells." (PMID 24913006, 2014). "In both lung cancer and Rhabdoid cell lines, we have found that HDAC9 and MEF2D bind to the BRM promoter." (PMID 24913006, 2014). "Our previous study reported that melatonin treatment could significantly mitigate lung cancer cell growth via inhibiting the HDAC9 signaling." (PMID 36163081, 2022). "However, in contrast, another study concluded that HDAC9 was expressed at a low level in lung cancer and attenuated cell proliferation." (PMID 31451695, 2019). "Besides, HDAC9 expression was positively associated with CD8+ cell counts significantly in the stroma samples of human lung cancer while lack of HDAC9 reduced inflammation and advocated progress of tumor by reducing CD8+ DC infiltration in the TME." (PMID 35514980, 2022). "For example, HDAC9 expression levels are reduced in lung cancer cells, the restoration of its levels in lung cancer cells severely attenuates their growth activity in vitro, reflecting that HDAC9 may be a tumor suppressor and its downregulation promotes lung carcinogenesis." (PMID 31365693, 2019). "Similar to lung cancer cell lines, we found that HDAC3, HDAC9, MEF2D and GATA3 controlled BRM silencing and that HDAC9 was overexpressed in Rhabdoid cancer cell lines." (PMID 24913006, 2014). "Like lung cancer, in these Rhabdoid studies, we found that HDAC3, HDAC9, GATA3 and MEF2D regulate BRM." (PMID 24913006, 2014). "Similar to our published studies with lung cancer, we found that BRM was also regulated by HDAC3, HDAC9, GATA3, and MEF2D in Rhabdoid tumors." (PMID 24913006, 2014). "HDAC9 expression was lower in lung cancer cells than in non-tumor epithelial cells and was significantly lower in adenocarcinomas." (PMID 34318404, 2021). "HDAC9 was not detectable by immunoblotting, which corresponds to a recent study showing significant down-regulation of HDAC9 in lung cancer cells and lung tumor tissue." (PMID 25608569, 2015). "Similar to lung cancer cell lines, GATA3 and MEF2D regulate both HDAC9 and BRM." (PMID 24913006, 2014). "Our results suggest that MEOX2, HDAC9, TWIST1, AhR and EVX1 overexpression from the 7p21 locus may be novel lung cancer or NSCLC tumor markers." (PMID 25460568, 2014).
lymphoma (136 papers, 2006 to 2026). A malignant (clonal) proliferation of B- lymphocytes or T- lymphocytes which involves the lymph nodes, bone marrow and/or extranodal sites. "We examined HDAC9 protein expression and copy number alterations in primary B-NHL samples, identifying high HDAC9 expression among various lymphoma entities and HDAC9 copy number gains in 50% of diffuse large B-cell lymphoma (DLBCL)." (PMID 27799148, 2016). "There is ample evidence directly linking HDAC9 to oncogenesis, including lymphomas." (PMID 29088719, 2017). "Thus, we concluded that Eμ-HDAC9 lymphomas and LPDs were derived from B-cell precursors, with evidence of transit through the GC or having experienced the GC reaction." (PMID 27799148, 2016). "Highest levels of HDAC9 expression were observed in the most aggressive lymphomas, such as DLBCL (both GC and non-GC subtypes) and MCL (77% and 83%, respectively, P=1.0, Fisher's exact test)." (PMID 27799148, 2016). "Hdac9, which is a chromatin-modifying enzyme functioning in early stages of B-cell development, showed B-to-A compartment activation with the positive correlation of expression level in pro-B cells but the negative correlation of expression level in lymphoma." (PMID 30894186, 2019).
glioma (119 papers, 2005 to 2026). A benign or malignant brain and spinal cord tumor that arises from glial cells (astrocytes, oligodendrocytes, ependymal cells). "The CNVs for the other four LARs–KAT6B (10q), SIRT1(10q), HDAC10 (22q), and HDAC9 (7q)–were highly associated with the risk signature and may be affected in chromosomal alterations such as 10q−, 22q− and 7+ in gliomas." (PMID 33718432, 2021). "Of the eleven annotated HDAC enzymes (HDAC1-11) only six are expressed in IDH1 mutant glioma tissue samples and patient-derived gliomasphere lines (HDAC1-4, HDAC6, and HDAC9)." (PMID 37528157, 2023). "In gliomas, high expression of HDAC9 promotes proliferation and tumorigenesis, in part by enhancing the EGFR signaling pathway to accelerate cell cycle." (PMID 36227941, 2022). "A model based on six HDAC genes (HDAC1, HDAC3, HDAC4, HDAC5, HDAC7, and HDAC9) can predict the overall survival of glioma patients well and these genes are potential therapeutic targets." (PMID 35545840, 2022). "Then, using six HDAC genes (HDAC1, HDAC3, HDAC4, HDAC5, HDAC7, and HDAC9), we established a prognostic model for glioma patients, and this prognostic model was validated in an independent cohort." (PMID 35545840, 2022). "In glioma, the high expression of HDAC9 can promote proliferation and tumor formation and accelerate the cell cycle in part by potentiating EGFR signaling pathways." (PMID 35545840, 2022). "HDAC9 was highly expressed in 472 out of 504 cases of glioma, and high expression very significantly correlated with reduced patient survival in French's data, p = 0.031." (PMID 25760078, 2015). "Western blot analysis showed that HDAC9 protein is expressed at a higher concentration in normal brain and low-grade gliomas than in high-grade gliomas, validating the data obtained by real-time PCR." (PMID 18713462, 2008). "Univariate Cox regression indicated that high expression levels of HDAC1, HDAC3, HDAC7 and HDAC9 were associated with poor OS of glioma, and elevated expression levels of HDAC4, HDAC5, HDAC6 and HDAC11 were associated with a favorable prognosis of glioma." (PMID 35545840, 2022). "Then, using six HDAC genes (HDAC1, HDAC3, HDAC4, HDAC5, HDAC7, and HDAC9), we established a prognostic model for glioma patients, and this prognostic model was validated in an independent cohort population." (PMID 35545840, 2022). "HDAC, HDAC1, HDAC2, HDAC3, HDAC5, and HDAC9 are among the HDACs that showed substantial alterations in glioma cells." (PMID 36146527, 2022). "The DFS-oriented study using GEPIA data showed that more transcripts of HDAC1 (HR:3.0, p < 0.0001), HDAC3 (HR:2.7, p = 2.1e−15), HDAC7 (HR:2.1, p = 3e−09), and HDAC9 (HR:1.5, p = 0.0026) accompanied with less DFS probabilities in glioma patients." (PMID 34540896, 2021). "Among the different classes of HDAC enzymes, HDAC1, HDAC2, HDAC3, HDAC5 and HDAC9 have undergone significant changes in glioma cells." (PMID 30498431, 2018). "Other clusters with positively co-correlated genes containedPPARGC1B and HDAC11, both strongly down-regulated in gliomas, and HDAC2, HDAC9 andSIRT6." (PMID 25791281, 2015). "The expression levels of HDAC1, HDAC3, HDAC7, and HDAC9 were significantly elevated in the glioma patients compared with the nontumor group." (PMID 35545840, 2022). "HDAC8 and HDAC9 expression levelswere not significantly changed in gliomas as compared to control patients." (PMID 25791281, 2015).
glioblastoma (111 papers, 2006 to 2026). The most malignant astrocytic tumor (WHO grade IV). "High HDAC9 mRNA levels are significantly associated with poor overall survival in medulloblastoma and glioblastoma (GBM) patients." (PMID 33513699, 2021). "This list includes cell surface expressed markers such as GPRC5, signaling molecules such PIK3R1 and the histone deacetylase, HDAC9, for which small molecule inhibitors are currently under investigation in glioblastoma clinical trials." (PMID 20423517, 2010). "HDAC9 protein is generally upregulated in glioblastoma patients who have a poor prognosis." (PMID 31013819, 2019). "Another study observed that HDAC9 was overexpressed in glioblastomas with a poor prognosis." (PMID 30701185, 2018). "Additionally, one large-scale sequencing study of the protein-coding genes in glioblastomas revealed mutations in two genes HDAC2 and HDAC9." (PMID 30701185, 2018). "Moreover, immunostaining assays revealed that the tumor tissues formed by HDAC9-knockdown cells had much weak Ki67 expression, suggesting that HDAC9 promoted the tumor formation of glioblastoma cells by accelerating cell proliferation." (PMID 25760078, 2015). "We found that HDAC9 is over-expressed in prognostically poor glioblastoma patients." (PMID 25760078, 2015). "Our studies revealed that HDAC9 promotes GBM growth via TAZ-mediated EGFR pathway activation, and provide the evidence for promising target for the treatment of glioblastoma." (PMID 25760078, 2015). "HDAC9 is overexpressed in GBM patients with poor prognosis and promotes tumor formation of glioblastoma via activation of the TAZ-mediated EGFR pathway." (PMID 28513547, 2017). "However, to our knowledge, the role of HDAC9 in glioblastoma remains unclear." (PMID 25760078, 2015). "Transcripts encoding the transmembrane glycoprotein, GPNMB, and histone deacetylase 9, HDAC9, are both over expressed in trisomic BG01V APCs and glioblastoma samples relative to diploid H9 APCs." (PMID 20423517, 2010). "We demonstrated that HDAC9 promotes tumor formation of glioblastoma via TAZ-mediated EGFR pathway activation, and provide the evidence for promising target for the treatment of glioblastoma." (PMID 25760078, 2015). "Therefore, further investigation is necessary to clarify the mechanism that HDAC9 up-regulated TAZ expression and promoted progression of glioblastoma." (PMID 25760078, 2015). "To address the importance of HDAC9 in cell growth and proliferation, we utilized the human glioblastoma cell lines U-87 MG (U87) and LN229, as well as primary cells obtained from GBM patients." (PMID 25760078, 2015).
ovarian carcinoma (111 papers, 2006 to 2026). A malignant neoplasm originating from the surface ovarian epithelium. "In order to explore the biological roles of HDAC9 in different histological subtypes of ovarian cancer, we selected serous ovarian cancer SKOV3 cells and endometrioid ovarian cancer A2780 cells for subsequent cell culture experiments." (PMID 35203583, 2022). "In order to investigate the roles of HDAC9 in ovarian cancer cells, we examined the effects of HDAC9 on cell proliferation and apoptosis." (PMID 35203583, 2022). "In order to verify the mechanism of HDAC9 on different types of ovarian cancers, further studies should concentrate on in vivo experiments." (PMID 35203583, 2022). "We investigated the expression of HDAC9 in human ovarian cancer tissues from 102 patients by immunohistochemical staining." (PMID 35203583, 2022). "The expression and function of HDAC9 in ovarian cancer are still unclear." (PMID 35203583, 2022). "HDAC9 may serve as a prognostic predictor for patients with ovarian cancer with different histological subtypes." (PMID 35203583, 2022). "Therefore, the prognosis of patients with ovarian cancer should consider not only the expression level of HDAC9 but also the histological subtypes of ovarian cancer and the expression of related genes." (PMID 35203583, 2022). "Our results showed that HDAC9 was mainly located in the nucleus of ovarian cancer cells." (PMID 35203583, 2022). "In this study, we investigated the potential roles of HDAC9 in ovarian cancer." (PMID 35203583, 2022). "HDAC9 may be a promising strategy for individualized treatment of patients with different histological subtypes of ovarian cancer by inhibiting tumor metastasis." (PMID 35203583, 2022). "Therefore, HDAC9 might be a promising biomarker for judging the prognosis of epithelial ovarian cancer." (PMID 35203583, 2022). "Therefore, HDAC9 may be a potential target for individualized treatment of patients with different histological subtypes of ovarian cancer." (PMID 35203583, 2022). "Thus, we speculated that HDAC9 controls FOXO1 activity by regulating the subcellular localization of FOXO1 in ovarian cancer cells." (PMID 35203583, 2022). "As our results show that HDAC9 was not involved in the proliferation and apoptosis of ovarian cancer cells." (PMID 35203583, 2022). "Our results indicate that HDAC9 might not be involved in cell proliferation and apoptosis of ovarian cancer cells." (PMID 35203583, 2022).
pancreatic cancer (109 papers, 2007 to 2025). "We also performed a Kaplan-Meier survival analysis, which revealed that the higher expression of HDAC1, HDAC2, HDAC7, and HDAC9 led to poor overall survival in pancreatic cancer patients." (PMID 39123441, 2024). "Within murine endothelial cells, STAT3 is activated by pancreatic cancer cell-derived pro-inflammatory and pro-angiogenic factors, leading to the up-regulation of HDAC9 which then enhances murine endothelial cell proliferation." (PMID 26586478, 2016). "In 2001, the Pancreatic Cancer Genetic Epidemiology group (PACGENE) identified susceptibility genes in linkage studies and succeeded in finding an association of 2 genetic loci with pancreatic cancer 7p21.1 (HDAC9) and 21q22.3 (COL6A2)." (PMID 33764904, 2021). "HDAC9 is also pro-angiogenic, and we recently reported that it is required for murine pancreatic cancer cells derived from the KRC (oncogenic Kras combined with loss of RB) genetically engineered mouse model to stimulate proliferation of SV40-transformed murine endothelial cells (SVEC4-10;)." (PMID 26586478, 2016).
colorectal cancer (104 papers, 2006 to 2026). A primary or metastatic malignant neoplasm that affects the colon or rectum. "However, there is no information on the role of NAP1L2, TONSL, HDAC9, and CHAF1B in colorectal cancer and were selected for further verification by qRT-PCR." (PMID 38212708, 2024).
hepatocellular carcinoma (83 papers, 2008 to 2025). A malignant tumor that arises from hepatocytes. "A high expression of HDAC9 contributes to poor overall survival of patients with hepatocellular carcinomas." (PMID 38920983, 2024). "A high expression of HDAC9 is positively related to stemness but negatively related to differentiation markers in hepatocellular carcinomas." (PMID 38920983, 2024). "We observed a minimum expression of HDAC9 in the normal hepatic cell line HC and well-differentiated HepG2 and HuH1 hepatoma cells that retain a hepatic phenotype, such as hepatic gene expression and drug-metabolizing activities." (PMID 32977608, 2020). "In hepatocellular carcinoma, HDAC9 correlates with PD‐L1 overexpression though its mechanism remains unclear." (PMID 41267925, 2025). "More recently, it was reported that HDAC9 is hypomethylated in hepatocellular carcinoma suggesting that epigenetic modifications could represent another way to overexpress HDAC9." (PMID 31099456, 2019). "High expression levels of HDAC9 and of other class IIa HDACs are significantly correlated with patient survival in hepatocellular carcinoma (HCC)." (PMID 33513699, 2021). "HDAC9 promotes the nuclear accumulation of FOXO1 and increases FOXO1 activity by deacetylation of FOXO1 protein in hepatocellular carcinoma." (PMID 35203583, 2022). "We confirmed preferential expression of HDAC9, a class II HDAC, in undifferentiated hepatoma cells and a positive correlation of gene expression between HDAC9 and dedifferentiation markers by database analysis of HCC patients." (PMID 32977608, 2020).